MANF (mesencephalic astrocyte derived neurotrophic factor)
Description:
Selectively promotes the survival of dopaminergic neurons of the ventral mid-brain. Modulates GABAergic transmission to the dopaminergic neurons of the substantia nigra (By similarity). Enhances spontaneous, as well as evoked, GABAergic inhibitory postsynaptic currents in dopaminergic neurons (By similarity). Inhibits cell proliferation and endoplasmic reticulum (ER) stress-induced cell death. Retained in the ER/sarcoplasmic reticulum (SR) through association with the endoplasmic reticulum chaperone protein HSPA5 under normal conditions. Stabilizes HSPA5/BiP in its substrate-bound ADP state, which facilitates HSPA5/BiP incorporation into chaperone-client complexes during endoplasmic reticulum stress, its interaction with HSPA5/BiP inhibits ATP binding to HSPA5/BiP and subsequent nucleotide exchange (By similarity). As a result acts as a repressor of the unfolded protein response (UPR) pathway (By similarity). Up-regulated and secreted by the ER/SR in response to ER stress and hypoxia. Following secretion by the ER/SR, directly binds to 3-O-sulfogalactosylceramide, a lipid sulfatide in the outer cell membrane of target cells. Sulfatide binding promotes its cellular uptake by endocytosis, and is required for its role in alleviating ER stress and cell toxicity under hypoxic and ER stress conditions. Essential for embryonic lung development (By similarity). Required for the correct postnatal temporal and structural development of splenic white pulp (By similarity). Required for the repair-associated myeloid response in skeletal muscle, acts as a regulator of phenotypic transition towards prorepair macrophages in response to muscle injury and as a result limits excessive proinflammatory signaling (By similarity). Represses RELA expression and therefore NF-kB signaling in the myocardium, as a result limits macrophage infiltration of injured tissue and M1 macrophage differentiation in response to myocardial injury (By similarity). Required for endochondral ossification in long bones and the skull during postnatal development (By similarity).
Synonyms: ARMET; ARP; DDDS
Tractability: Antibody: UniProt places it where antibodies can reach, with high confidence; its Gene Ontology location is reachable by antibodies, with high confidence; UniProt predicts a signal peptide or a membrane-spanning region. PROTAC: ubiquitination databases record sites on it; its protein half-life has been measured.
Gene: Protein-coding gene on chromosome 3 (51,385,291 to 51,389,397, forward strand). Ensembl gene ENSG00000145050.
Subcellular location: Secreted; Endoplasmic reticulum lumen; Sarcoplasmic reticulum lumen
Subcellular location (Human Protein Atlas): Endoplasmic reticulum; Predicted to be secreted
Pathways (Reactome):
Hemostasis: Platelet degranulation
Gene Ontology:
Molecular function: growth factor activity; protein binding; RNA binding; sulfatide binding
Biological process: ATF6-mediated unfolded protein response; regulation of response to endoplasmic reticulum stress; dopaminergic neuron differentiation; neuron projection development
Cellular component: endoplasmic reticulum; endoplasmic reticulum lumen; extracellular region; nucleus; sarcoplasmic reticulum lumen; cytosol
Genetic constraint (gnomAD): Loss-of-function variants: 9 observed, 16.55 expected, observed/expected ratio (o/e) 0.54, 90% interval 0.33 to 0.95. The upper end of that interval is the gene's LOEUF score, 0.95, which puts it in group 4 of 6, group 1 being the genes least tolerant of losing a copy. Missense variants: 225 observed, 214.72 expected, observed/expected ratio (o/e) 1.05, 90% interval 0.94 to 1.17. Synonymous variants: 89 observed, 82.01 expected, observed/expected ratio (o/e) 1.09, 90% interval 0.91 to 1.29.
Homologues: Orthologues: chimpanzee MANF (99% identical), macaque MANF (98% identical), mouse Manf (96% identical), rabbit MANF (96% identical), guinea pig MANF (94% identical), dog MANF (93% identical), rat Manf (85% identical), pig MANF (84% identical), tropical clawed frog manf (73% identical), zebrafish manf (69% identical), Drosophila melanogaster Manf (48% identical), Caenorhabditis elegans manf-1 (44% identical). Paralogues in human: CDNF (57% identical).
Diseases named in the same sentence as MANF in open-access papers:
MANF is named in the same sentence as 149 diseases in open-access papers, as found by Europe PMC text mining. Sharing a sentence is not in itself a finding about the gene and the disease. The quoted sentences say what the papers report.
Parkinson disease (32 papers, 2013 to 2025). A progressive degenerative disorder of the central nervous system characterized by loss of dopamine producing neurons in the substantia nigra and the presence of Lewy bodies in the substantia nigra and locus coeruleus. "Evidence suggests that MANF rescues neuronal loss in several neurological disorders, such as Alzheimer’s disease, Parkinson’s disease, and cerebral ischemia." (PMID 39289348, 2024). "In D. melanogaster, the Manf homolog DmManf is required for the maturation and maintenance of dopaminergic neurites during the embryonic stage, implying the importance of MANF in Parkinson’s disease, where dopaminergic neuronal loss is the major factor." (PMID 35783104, 2022). "Many groups, including ours, have proved that MANF rescues neuronal loss in several neurological disorders, such as Parkinson’s disease and cerebral ischemia." (PMID 30760285, 2019). "Notably, elevated blood levels of MANF in Parkinson’s disease patients suggest its potential as a diagnostic biomarker." (PMID 37751132, 2023). "It has also been reported that MANF attenuated the neuronal lesion in MPTP/MPP+-induced Parkinson's disease mice, which might be associated with the inhibition of oxidative stress and the amelioration of mitochondrial function." (PMID 32724497, 2020). "For example, experimental models of Alzheimer’s Disease, Parkinson’s Disease and stroke have demonstrated that MANF is a neuroprotector." (PMID 40622554, 2025). "A study revealed that patients with Parkinson’s disease showed significantly higher levels of MANF than HCs." (PMID 38216957, 2024). "MANF was also shown to protect neurons from ER stress-induced damage in Parkinson’s disease (PD), Alzheimer’s disease (AD), and stroke." (PMID 37048105, 2023). "In Parkinson’s models, MANF manages cellular stress via endoplasmic reticulum regulation and activates antioxidant pathways through PI3K/Akt/GSK3β and AMPK/mTOR pathway to enhances mitochondrial function." (PMID 37751132, 2023). "This review discusses MANF signaling in neurodegenerative conditions with specific emphasis given to its overall effect and mechanisms of action in experimental models of Parkinson’s disease, Alzheimer’s disease, and stroke." (PMID 37048105, 2023). "In the in vivo 6-OHDA toxin model of Parkinson’s disease, the recombinant MANF protects the dopaminergic cell bodies of the substantia nigra." (PMID 35783104, 2022). "CDNF and MANF have cytoprotective effects in different animal disease models, such as Parkinson’s disease, ischemic stroke, and spinocerebellar ataxia." (PMID 35129674, 2022). "In comparison, neuron-specific MANF expression in vivo improved the outcome in the 6-OHDA toxin model of Parkinson’s disease by reducing the levels of p-eIF2a, ATF4, CHOP, XBP1s, GRP78, and ATF6α." (PMID 35783104, 2022). "Previous studies demonstrated that MANF is a protective factor for dopamine neurons in animal models of Parkinson disease, cardiac myocytes in myocardial infarction, cortical neurons in ischemic stroke, and retinal cells in models of photodamage." (PMID 33299977, 2020). "Exogenous mesencephalic astrocyte-derived neurotrophic factor (MANF) is neuroprotective in animal models of Parkinson’s disease and stroke, but the function of endogenous MANF in neurons is still elusive." (PMID 32005751, 2020). "In rats, exogenously added and striatally overexpressed MANF protects dopamine neurons in the 6-hydroxydopamine model of Parkinson’s disease." (PMID 32005751, 2020). "Whereas exogenous MANF has demonstrated protection of dopamine neurons in animal models of Parkinson’s disease, the function of endogenous MANF in the dopamine neuron maintenance in mice is not known." (PMID 32005751, 2020). "Namely these neurons degenerate in the Parkinson’s disease and are rescued by MANF and CDNF in the animal experiments." (PMID 30234112, 2018).
Parkinson disease (continued). "Intracranially (extracellularly) injected MANF effectively protected dopaminergic neurons in a rat model of 6-hydroxydopamine induced Parkinson’s disease and the ischemia model, thereby suggesting it to function as a secreted neurotrophic factor." (PMID 29896089, 2018). "Emerging evidence suggests that MANF affords protection in several disease conditions, including Parkinson’s disease, ischemic stroke, and retinal degeneration." (PMID 29378605, 2018). "Brain injection of recombinant MANF protein has been previously shown neuroprotective in a Parkinson disease rat model." (PMID 28924165, 2017). "Based on their DA neuron survival-promoting and neuro-restorative effects, the MANF/CDNF family of proteins has therapeutic potential for treatment of Parkinson’s disease." (PMID 24019940, 2013). "MANF was originally identified in the rat ventral mesencephalic cell line in 2003, and later studies have reported that MANF has a neuroprotective effect in Parkinson’s disease and ethanol-induced neurodegeneration." (PMID 40603319, 2025). "Increased serum MANF protein levels have been reported in patients with Parkinson’s disease diagnosed on average 6 years ago, indicating that circulating MANF levels may be altered in chronic CNS disease." (PMID 38229173, 2024). "Summary of preclinical studies of MANF in rodent Parkinson’s disease models." (PMID 37555005, 2023). "Notably, both CDNF and MANF display neuroprotective effects that extend beyond Parkinson’s disease, embracing conditions like cerebral ischemia and spinocerebellar ataxia." (PMID 37751132, 2023). "MANF has also shown benefit in Parkinson's and Alzheimer's disease by protecting dopaminergic neurons and reducing intracellular α-synuclein aggregates in Parkinson's disease and mitigating Aβ1-42-induced neuronal cell death in Alzheimer's disease." (PMID 38012707, 2023). "MANF has been shown to protect against many types of cerebral injuries in in vivo disease models, including ischemic stroke, hemorrhagic stroke, traumatic brain injury, and Parkinson’s disease." (PMID 35783104, 2022). "In addition to diabetes mellitus, cytoprotective effects of MANF have also been shown in animal models of Parkinson disease, ischemia, and retinal neurodegenerative diseases." (PMID 33299977, 2020). "MANF has also been used in rat models of Parkinson’s disease." (PMID 31044581, 2019). "Previously, mesencephalic astrocyte-derived neurotrophic factor (MANF) and cerebral dopamine neurotrophic factor were identified as a new family of neurotrophic factors protecting dopamine neurons in animal models of Parkinson’s disease." (PMID 29082311, 2017). "Therefore, CDNF and MANF have been hypothesized to be survival factors for dopamine neurons, which degenerate in Parkinson’s disease and hence lead to the characteristic motor symptoms." (PMID 35129674, 2022). "Mesencephalic astrocyte-derived neurotrophic factor (MANF), an 18 kD, ER soluble protein, can exert protective function in Parkinson’s disease and ischemic stroke, and regulate immune homeostasis in aging and retinal regenerative therapies in animal models." (PMID 37838725, 2023). "In rodent Parkinson’s disease models, CDNF and MANF have been shown to promote the survival of dopamine neurons." (PMID 35129674, 2022). "Research has shown that, in a rat model of Parkinson's disease, neuronal CDNF and MANF protect dopaminergic neurons and support nerve repair." (PMID 32508943, 2020). "Exogenous MANF and CDNF possess therapeutic properties in several neurological disease models, including Parkinson’s disease and stroke." (PMID 31044581, 2019). "Most importantly, MANF and especially CDNF are neurorestorative in the animal models of Parkinson’s disease." (PMID 30234112, 2018). "Recombinant human MANF (HsMANF) and CDNF (HsCDNF) protect and repair midbrain dopaminergic (DA) neurons in rodent models of Parkinson’s disease in vivo." (PMID 24019940, 2013).
Parkinson disease (continued). "Cerebral dopamine neurotrophic factor (CDNF), a paralog of mesencephalic astrocyte-derived neurotrophic factor (MANF), was first characterized in 2007 as a trophic factor for midbrain dopamine neurons in a rat 6-hydroxydopamine (6-OHDA) model of Parkinson’s disease." (PMID 36012764, 2022). "While MANF has been effective in cells and some animal models, CDNF has shown efficacy in rodent models of the disease, and CDNF is currently in Phase I/II clinical trials for Parkinson’s disease." (PMID 31044581, 2019). "Both MANF and CDNF have positive effects on models of Parkinson’s disease, however, to determine whether this is through an ER-related mechanism needs further study." (PMID 31044581, 2019). "MANF and its homolog, the cerebral dopamine neurotrophic factor (CDNF), have been identified to protect and rescue midbrain dopaminergic neurons in the rat 6-OHDA model of Parkinson’s disease." (PMID 30760285, 2019). "Both MANF and CDNF have mainly been used in models of Parkinson’s disease." (PMID 31044581, 2019). "Mesencephalic astrocyte-derived neurotrophic factor, one type of novel NTF family, has been reported to display cytoprotective effects in myocardial infarction and neurological diseases, such as Parkinson’s disease or ischemic stroke." (PMID 29896089, 2018). "Glial cell line-derived neurotrophic factor (GDNF), cerebral dopamine neurotrophic factor (CDNF), and mesencephalic astrocyte-derived neurotrophic factor (MANF) have shown neuroprotective and restorative effects on nigral dopaminergic neurons in various animal models of Parkinson’s disease." (PMID 29349573, 2018). "In human blood cells, MANF protein has been detected mostly in platelets, to some extent in leukocytes, and very little in red blood cells but at least in the case of Parkinson’s disease patients the increased serum MANF levels were not originating from the blood cells." (PMID 38229173, 2024).
diabetes (31 papers, 2016 to 2025). "Conventional MANF knockout mice develop diabetes, hearing loss, liver defects, and impaired neural migration and neurite outgrowth, with activated UPR." (PMID 41339935, 2025). "These phenotypes – diabetes, growth defect, and hearing loss – are noticeably similar to symptoms found in human subjects with MANF loss-of-function mutations." (PMID 37555005, 2023). "MANF-deficient mice display ER stress in the pancreas and develop diabetes due to progressive postnatal reduction in β cell mass." (PMID 36830970, 2023). "Homozygous loss-of-function mutations of the human MANF gene were reported as a cause of childhood diabetes, and were mechanistically connected to ER stress and impaired beta cell function." (PMID 34907395, 2022). "Our Manf−/− mice present similar phenotypes to humans, including diabetes, hearing loss and growth defects, indicating that our MANF mouse models are biologically relevant when examining the biological function of MANF in mammals." (PMID 35129674, 2022). "It has been proposed that chronic, unresolved UPR activation in pancreatic beta cells is the underlying cause of MANF-deficient mice developing diabetes." (PMID 33460650, 2021). "Reduced MANF expression in β-cells seems to underlie enhanced susceptibility for β-cell apoptosis and diabetes in mice and humans." (PMID 31781038, 2019). "MANF-deficiency in mice results in β-cell death and diabetes, and a severe diabetes-independent growth defect." (PMID 31781038, 2019). "Further supporting this, MANF expression is reduced in diabetes-susceptible mice compared with diabetes-resistant mice." (PMID 30032427, 2018). "Surprisingly, deletion of MANF in mice leads to a progressive postnatal reduction of pancreatic β-cells followed by insulin-deficient diabetes." (PMID 29082311, 2017). "Complete and pancreas-specific deletion of MANF caused severe diabetes characterized by postnatal reduction of β-cell mass, due to their increased apoptosis and decreased proliferation, indicating that MANF is essential for the maintenance of β-cells." (PMID 27356471, 2016). "In addition to diabetes, patients with loss of function mutations in the MANF gene showed growth retardation, microcephaly and hearing loss." (PMID 35129674, 2022). "Interestingly, loss of MANF in humans results in diabetes due to increased ER stress in the pancreatic beta cells analyzed in human stem cell-derived differentiated beta-like cells with a homozygous MANF mutation." (PMID 35129674, 2022). "Other ER-resident proteins implicated in monogenic diabetes include mesencephalic astrocyte-derived neurotrophic factor (MANF) and immediate early response 3 interacting protein 1 (IER3IP1); they may directly or indirectly modulate the UPR." (PMID 33967960, 2021). "Mutated MANF gene was reported in patients with neurological abnormalities and diabetes." (PMID 34575854, 2021). "MANF-deficient mice develop diabetes due to ER stress-mediated pancreatic β-cell death." (PMID 33299977, 2020). "Interestingly, a patient with a homozygous missense mutation in the MANF gene likely leading to a null mutation was presented with microcephaly and diabetes." (PMID 32005751, 2020). "Our study elucidates the role of MANF as a protective and mitogenic growth factor for adult human beta cells that could potentially be used to prevent or reverse beta cell loss in diabetes." (PMID 30032427, 2018). "Numerous studies have highlighted the potential of MANF as a therapeutic agent for diabetes mellitus (DM), making it essential to understand the mechanisms underlying MANF’s functions." (PMID 39666939, 2024). "Moreover, global MANF-deficiency in mice results in severe diabetes-independent growth retardation." (PMID 31781038, 2019). "Our finding further emphasizes the critical role of MANF, a promising therapeutic candidate for diabetes, in the transgenerational inheritance of glucose metabolic dysfunction." (PMID 40041941, 2025).